GSK3B (glycogen synthase kinase 3 beta)
Diseases named in the same sentence as GSK3B in open-access papers (continued):
Sharing a sentence is not in itself a finding about the gene and the disease.
tumor (continued). "Even though the PDL1/GSK3β immune complex has been observed in tumor cells, it is still unclear whether this interaction occurs in the brain and whether GSK3β is the direct downstream target of PD1/PDL1 to regulate tau hyperphosphorylation in AD." (PMID 34977020, 2021). "Whether GSK3β plays a primarily oncogenic or tumour suppressor role appears to depend on the cellular context and tumour type." (PMID 34739494, 2021). "In contrast, GSK3β functions as a tumor suppressor in other cancers such as breast cancer." (PMID 34403222, 2021). "Blocking the actions of GSK-3β by lithium would result in inhibition of tumor growth." (PMID 34832080, 2021). "Moreover, PBMF treatment remarkably increased the protein expression levels of GSK-3β and E-cadherin but notably reduced those of Ki-67 and N-cadherin in tumor tissues." (PMID 33964908, 2021). "Previous studies showed that patients with overexpression of N-Myc downregulated gene 1 (NDRG1) in GBM tumor cells exhibited better prognoses, and its downregulation increased the expression level of glycogen synthase kinase 3β (GSK3β), which promotes cell proliferation." (PMID 33671112, 2021). "It has also been reported that prodigiosin inhibits the phosphorylation of GSK‐3β, restraining β‐catenin‐mediated Wnt activation and subsequent transcriptional activation of prosurvival genes, such as cyclin D1, slowing tumor progression in a breast cancer tumor model mice." (PMID 33841802, 2021). "GSK3β acts as a suppressor of β-catenin nuclear translocation in the Wnt/β-catenin signaling pathway, which is highly activated in CSCs of various cancer types, such as breast cancer." (PMID 34403222, 2021). "•GSK-3β plays an important role in regulating T cell-mediated anti-tumor immunity." (PMID 34142056, 2021). "Signalling through GSK3b, therefore, may be a key regulator of the c-Met shift that enables metastatic tumour cells to produce new tumours at secondary sites." (PMID 34831291, 2021). "Thus, GSK-3β has the potential to directly invigorate tumor infiltrating T cells and NK cells by enhancing proliferative capacity and cytotoxicity." (PMID 34356465, 2021). "Active GSK3β can act as a tumor suppressor as it participates, together with other members of the destruction complex including APC (Adenomatous Polyposis Coli), AXIN1 and CK1 (Casein Kinase 1), in phosphorylation and subsequent degradation of the oncogenic β-catenin protein." (PMID 34064046, 2021). "Observation results of tumour formation in nude mice indicated that overexpressed GSK3β significantly reduced tumour volume and weight, which could be restored by up‐regulating c‐Myc expression." (PMID 33533172, 2021). "Taken together, depletion of TAM-derived exosomal miR-29a-3p could lead to downregulation of PD-L1 expression via the FOXO3-AKT/GSK3β axis, thereby inhibiting tumor formation and immune escape in vivo." (PMID 34589270, 2021). "The authors also emphasize the prooncogenic effects of GSK3β on the NFkB pathway, although it has previously been said that those effects could be tumor suppressive as well." (PMID 32767962, 2021). "In contrast, some studies have suggested that GSK-3β may promote tumorigenesis and tumor development." (PMID 34966427, 2021). "Interestingly, more and more studies imply that the GSK-3β/β-catenin pathway exerts a function in tumor development." (PMID 34555811, 2021). "Thus, the role of GSK3β in malignancy is determined by the context of substrates as well as tumor types." (PMID 34433808, 2021). "Hyperactive AKT then inactivates GSK3β and thereby blocks GSK3β-mediated PD-L1 degradation, which results in excessive PD-L1 expression on malignant hepatocytes, leading to PD-L1/PD-1 axis-mediated tumor immune evasion and, ultimately, HCC development." (PMID 34108491, 2021). "Furthermore, recent evidence has revealed that a variety of small molecule inhibitors that targeting the PI3K/AKT/GSK3β axis attenuated tumor progression." (PMID 34595179, 2021).
tumor (continued). "GSK3β-mediated phosphorylation can render substrates as targets for proteasomal destruction, thus inactivating various oncogenic proteins, such as β-catenin and c-Myc, to suppress tumor development." (PMID 34433808, 2021). "In summary, overexpression of the GSK3β, β-Catenin, STAT3, and CD44 oncogenes and downregulation of the miR-135b tumor suppressor in GBM tumor samples compared to adjacent normal tissue were associated with poor patient prognoses, stemness, and therapeutic resistance." (PMID 33671112, 2021). "Treating DHHC20-deficient NCI-H23 cells with the proteasome inhibitor MG132 or GSK3β inhibitor CHIR-9002 partially restored Myc protein levels, indicating the direct involvement of GSK3β-directed Myc proteasomal degradation in palmitoylation-dependent tumour growth." (PMID 34610265, 2021). "Unlike these differences, cell surface PD-1 expression was measured on tumor-infiltrating lymphocytes (TILs) and showed a clear reduction in the double and Gsk3b cKO mouse cells and a lesser reduction in TILs from the Gsk3a cKO mice, consistent with the Pdcd1 gene expression data from the spleen." (PMID 34142056, 2021). "GSK-3β is especially responsible for tumor invasion and treatment resistance." (PMID 35317111, 2021). "The influence of GSK3β on tumor formation and promotion is still controversial." (PMID 34064046, 2021). "Although the samples we examined are small, we could consistently demonstrate that GSK-3β is increased in almost every tumor and upregulation of ≥1.5-fold is seen in 66.7% HCC." (PMID 31938062, 2020). "RNA-seq data of COAD and LIHC from TCGA showed that GSK3B were also upregulated in tumor tissue." (PMID 32029792, 2020). "Importantly, these therapy resistant tumor types share the same pathways with their capacity of invasion, suggesting that GSK3β forms a pernicious cycle between tumor invasion and resistance to therapy in the refractory cancer types." (PMID 32503133, 2020). "Moreover in this study, administration of docosahexaenoic acid (DHA) was shown to dephosphorylate GSK-3β (increase in enzymatic activity), reduce the expression of β-catenin protein and attenuate the growth of tumor cells again." (PMID 32140709, 2020). "In addition, pictilisib inhibited differentiation of osteoclasts and bone resorption in vitro and tumor-related osteolysis in vivo via inhibition of the PI3K/AKT/GSK3β and NF-κB pathways." (PMID 33659212, 2020). "We found that inactivation of GSK-3β by tideglusib could significantly shrink tumor (22.3% inhibition), inhibit Ki-67 expression (14.2%) and induce caspase 3 activation (9.1%), further supporting that overexpression of GSK-3β might be a tumor promoter in HCC." (PMID 31938062, 2020). "Disclosing the role and mechanism of GSK-3β in tumor will help develop new therapeutic strategy." (PMID 31938062, 2020). "GSK3β participates in tumor cell survival, proliferation, invasion and therapy resistance." (PMID 32503133, 2020). "Conversely, this indicates that GSK3β renders tumor cells insensitive to cancer therapy." (PMID 32503133, 2020). "Thus, in this scenario, GSK-3β was functioning as a tumor suppressor in CRC cells and altered NAT10 localization was associated with a poorer clinical prognosis." (PMID 32365809, 2020). "In contrast to the notion of GSK3β as a tumor suppressor, a growing number of studies over the past 15 years by our group and many others have instead shown that aberrant expression and activity of GSK3β facilitates the progression of various cancer types." (PMID 32503133, 2020). "GSK3β has long been recognized to suppress tumor development and progression." (PMID 32503133, 2020). "Based on its physiological functions against major proto-oncogenic pathways driven by Wnt/β-catenin, hedgehog, notch and c-Myc signaling, as well as against epithelial-to-mesenchymal transition, GSK3β has long been recognized to suppress tumor development and progression." (PMID 32678196, 2020).
tumor (continued). "The role of GSK3β inhibition in Th17 cells in the tumor microenvironment is less well-studied." (PMID 32850361, 2020). "Pro-oncogenic activity for GSK3β is supported by the observation that deregulated GSK3β sustains tumor cell survival, proliferation and invasion by abrogating distinct tumor suppressor pathways and by enhancing cell immortality as well as the machinery for cell motility and migration." (PMID 32503133, 2020). "Targeting GSK-3β could significantly inhibit tumor growth of subcutaneous or orthotopical xenografts." (PMID 31938062, 2020). "Despite recognized roles against several proto-oncoproteins and mediators of the epithelial–mesenchymal transition, deregulated GSK3β also participates in tumor cell survival, evasion of apoptosis, proliferation and invasion, as well as sustaining cancer stemness and inducing therapy resistance." (PMID 32503133, 2020). "Importantly, a growing body of literature shows that GSK3β inhibitors modulate the immune system in autoimmune and neoplastic disease contexts." (PMID 32850361, 2020). "In this scenario, GSK-3β was functioning as a tumor suppressor and could be activated by the natural product tetrandrine." (PMID 32365809, 2020). "Therefore, GSK3β inhibition in AML has the dual effects of directly suppressing tumor cell survival and proliferation, and of activating innate NK cells to destroy the tumor cells." (PMID 32503133, 2020). "In vitro experiments revealed that GPNCA silencing markedly inhibits tumor cell proliferation via regulation of GSK3B, suggesting that drugs targeted to GPNCA may hold potential considerable value for anti-cancer therapy." (PMID 32029792, 2020). "GSK-3β is active and can inhibit cell proliferation which inhibits tumor growth." (PMID 32365809, 2020). "These clinical observations on lithium treatment suggest that ATP-non-competitive inhibition of GSK3β is unlikely to cause tumor development and progression." (PMID 32503133, 2020). "Moreover, exposure to a target antigen increased cytotoxic efficacy and tumor-killing ability in GSK-3β-inhibited IL13-CAR-T cells." (PMID 32526891, 2020). "Also, the Akt/GSK-3β pathway triggers a network that positively regulates tumor progression by activating β-catenin." (PMID 32514243, 2020). "Importantly, reactivation of RARβ-dependent signaling that is inhibited by overexpression of GSK-3β returns profoundly unexpected sorafenib treatment outcome (tumor inhibition raised sharply from 48.3% to 93.4%)." (PMID 31938062, 2020). "It was recently demonstrated that overexpression of GSK-3β can confer tumor growth." (PMID 31938062, 2020). "Treatment with GSK3β inhibitors could prevent the emergence of chemotherapy resistance and tumor recurrence." (PMID 30845991, 2019). "GSK3β/β-Catenin signaling is critical for tumor growth, maintenance, and metastasis." (PMID 31722716, 2019). "They suggested that GSK3β acts as a tumour promoter and a potential therapeutic target." (PMID 30446846, 2019). "On the one hand, evidence indicates that GSK3β functions as a tumor suppressor in the breast." (PMID 31744046, 2019). "lncRNA small nucleolar RNA host gene 5 (SNHG5) was found acting as a competing endogenous RNA competitively binding with miR-26a-5p and thereby modulating the de-repression of downstream target GSK3β, functionally promoted tumor metastasis and induced EMT via activating Wnt/β-catenin pathway." (PMID 31555129, 2019). "GSK-3β is known to regulate tumor migration and invasion through control of EMT." (PMID 30709379, 2019). "As a downstream regulator, GSK-3β affects glycogen metabolism, participates in a variety of signal transduction pathways and plays an important role in embryo development, cell differentiation and tumor formation." (PMID 31024348, 2019).
tumor (continued). "It is has been widely reported that PI3K/AKT signaling pathway regulates EMT by promoting the phosphorylation of downstream target proteins (Bad, Caspase9, NF‐κB, GSK‐3β, mTOR, p21Cip1, p27 Kip1, etc.)to further mediates tumor proliferation, invasion and metastases 46-48." (PMID 31410208, 2019). "Our data suggests that rather than targeting IRF1 to reduce overall abundance – which would impede its tumour suppressive function, GSK3β-Fbxw7α aid in the timely clearance of DNA-bound IRF1 to support additional rounds of transcription and thus downstream phenotypes such as reduced proliferation." (PMID 30854564, 2019). "PI3K p110α is involved in tumor growth, hypoxia, metastasis, or cell communication by increasing the tight junction formation and the activity of glycogen synthase kinase-3 beta (GSK-3β) to promote cyclin D1 expression." (PMID 31888636, 2019). "In this regard, previous studies have shown that SGKs might modulate tumor growth via regulating cyclin D1 expression, GSK3-β/β-catenin cascade as well as epithelial-mesenchymal transition (EMT) in HCC cells." (PMID 30975125, 2019). "Nevertheless, Claspin stabilization and Chk1 activation after GSK3-β inhibition might contribute to promoting survival, and thereby counteracting tumour removal." (PMID 31362447, 2019). "AKT/GSK-3β/β-catenin signaling pathway was an important tumor regulatory signaling pathway." (PMID 30828264, 2019). "Reversely, the repression of GSK3β might intensify Wnt/β-catenin activation, promoting tumor growth and metastasis." (PMID 31555129, 2019). "Subsequently, we observed that chemically synthesized cinobufotalin (CB) strongly increased FOXO1-induced DDP chemosensitivity by reducing MYH9 expression, and the reduction in MYH9 modulated GSK3β/β-catenin and its downstream tumor stemness and EMT signal in NPC." (PMID 31754475, 2019). "Additionally, the PI3K inhibitor, LY294002, significantly inhibited the phosphorylation of AKT and GSK-3β which consequently decreased the nuclear localization of β-catenin and therefore suppressed the tumor-promoting effects of PA." (PMID 30717785, 2019). "In this study, we found that circGSK3β could inhibit the biogenesis of its parental protein, GSK3β, which functions as a tumor suppressor by inhibiting the Wnt/β-catenin pathway-mediated cell metastasis." (PMID 31722716, 2019). "The cytotoxicity of the N. alba leaf and root extracts, due to the presence of bioactive compounds as corilagin, chlorogenic acid or caffeic acid can be explained on the one hand by inhibition of gene β-catenin and induction of genes as GSK-3β, promoting the tumor cell apoptosis." (PMID 31877815, 2019). "We found that AZD5363 drastically inhibited E2-enhanced expression of p-4Ebp1, p-mTor, and p-Gsk3β, and that of Vim and p-Fra1, suggesting that AZD5363 efficiently suppresses estrogen-enhanced Akt pathway and EMT program in Brca1 deficient tumor cells." (PMID 29996906, 2018). "Beyond that, a study showed that GADD45A promotes Myc-driven breast carcinogenesis by negatively regulating matrix metalloproteinase 10 (MMP10) through GSK-3β (Glycogen synthase kinase 3 beta)/β-catenin signaling, resulting in increased tumor vascularization and growth." (PMID 30128181, 2018). "Furthermore, NK cells expanded ex vivo in the presence of a GSK-3β inhibitor exhibit a more mature phenotype and significantly higher anti-tumor activity, suggesting GSK-3β as a promising therapeutic target for NK cell-based therapy." (PMID 30250471, 2018). "However, in some cases, inhibition of GSK3β activity also inhibits tumor growth and sensitizes cells to chemotherapy." (PMID 30275459, 2018).
tumor (continued). "Inhibition of GSK3β suppressed tumorigenesis by inhibiting cell proliferation and inducing apoptosis, suggesting that GSK3β could be developed as a tumor promoter and a potential therapeutic target in NSCLC47." (PMID 29789524, 2018). "The roles of GSK-3β in cancer and tumor progression remain controversial." (PMID 29445085, 2018). "The RKIP/GSK3β axis was first reported by Al Mulla and colleagues to have a critical impact in sustaining GSK3β activity, as a suppressor of multiple oncogenic pathways, including those of Wnt and cyclin D, known to be essential for tumor proliferation, progression, and metastasis." (PMID 30149591, 2018). "The role of GSK-3β in cancer remains complex and controversial since GSK-3β may act as a tumor-promoter as well as tumor-suppressor." (PMID 30213025, 2018). "We additionally investigated whether BS and GEM alone or in combination could downregulate the levels of EMT markers and Akt/GSK-3β pathway in the tumor tissue." (PMID 30670971, 2018). "Other findings, in an in vivo mouse model, support the hypothesis that the stabilization of PD-L1 by the inactivation of GSK3β increases tumor immunosuppressive function, promoting tumor cell survival." (PMID 30213113, 2018). "GSK3B is a main component of the Wnt signaling pathway and may behave like a tumor promoter or suppressor depending on the cancer type." (PMID 30020984, 2018). "Thus, our findings clearly show that GSK-3β positively regulates c-FLIPL levels in HCC, supporting the concept that GSK-3β acts as a tumor promoter by enhancing c-FLIPL expression in HCC." (PMID 29445085, 2018). "Our experimental results showed that GSK-3β is intimately associated with the degree of differentiation in NSCLC but is not correlated with tumor TNM staging or lymph node metastasis." (PMID 29793508, 2018). "It was found that expression levels of ERp29 in tumor specimens were negatively correlated with the PI3K/Akt/GSK3β and Akt-mTOR signaling pathway-activated gene signatures and positively correlated with the PI3K/Akt/GSK3β and Akt-mTOR signaling pathway suppressed gene signatures." (PMID 28874138, 2017). "PI3K/AKT/GSK3β/β-catenin signaling pathway exists in a variety of tumor cells." (PMID 29358963, 2017). "Consequently, this up-regulation was able to enhance the proliferation of ER-negative breast cancer cells in vitro via the GSK3β/β-catenin/cyclin D1 pathway and was able to promote tumor development in vivo." (PMID 29216929, 2017). "We also explored whether GSK3β activity in clinical tumor tissues influences the survival of GBM patients to rationalize the targeting of GSK3β." (PMID 28423558, 2017). "Additionally, MM54 treatment led to a significant increase in phospho-GSK3β positive cells within the tumour." (PMID 29053791, 2017). "Collectively, we speculated that HCCLM3 cells secreted CTHRC1 into the tumor microenvironment by down-regulating miR-155-5p and then attenuated cancer cell growth and metastasis by activating GSK-3β-involved Wnt/β-catenin signaling." (PMID 29234238, 2017). "In addition, poorly differentiated and non-differentiated tumours had significantly higher levels of GSK3β than tumours which were well and moderately differentiated." (PMID 28930226, 2017). "GSK-3β inhibition leads to β-catenin activation and tumor cell proliferation." (PMID 29379583, 2017). "We identified three tumor suppressor genes associated with Wnt pathway, namely, DKK3, KLF4 and GSK3β, that might be the potential targets of miR-92a." (PMID 29254202, 2017). "The levels of miR-410 and Gsk3β might be correlated to clinicopathological differentiation in NSCLC tumor specimens." (PMID 28076327, 2017). "Overexpression of ZNRF3 inhibited cell growth and attenuated the tumor-promoting effects of miR-146a via inhibition of GSK-3β/β-catenin signaling, indicating that miR-146a may function as a tumor suppressor and represent a potential biomarker for OS patients." (PMID 29088784, 2017).